SIRT1 (sirtuin 1)
Diseases named in the same sentence as SIRT1 in open-access papers (continued):
Sharing a sentence is not in itself a finding about the gene and the disease.
diabetes (continued). "SIRT1 deficiency can lead to metabolic disorders such as diabetes, nonalcoholic fatty liver, cardiovascular disease, and neurodegeneration." (PMID 36008973, 2022). "It is important to note that the altered AMPK/SIRT1 pathways have been linked to diabetes and have been proposed to explain why PGC-1α activity is reduced." (PMID 36262282, 2022). "Specifically, the anti-aging gene Sirtuin 1 repression is associated with the onset of diabetes, cardiovascular disease and sarcopenia, which in turn leads to BMI variation, eventually resulting in Aβ deposition." (PMID 35936766, 2022). "With this centralized role in regulating the response of metabolic factors to cellular energy availability, it is unsurprising that variation in SIRT1 has been linked to, among other things, the development of diabetes." (PMID 35435227, 2022). "As impaired NO production and vasodilation are associated with diabetes-accelerated endothelial dysfunction, resveratrol is presumed to exert protective effects via upregulating SIRT1-mediated eNOS-dependent vasodilatory effects." (PMID 35739982, 2022). "Sirt1 is a well-studied regulator of metabolic homeostasis and has been implicated in the development of insulin resistance and diabetes in mammals and Drosophila44,45." (PMID 35347148, 2022). "To model the hyperglycemia that is commonly associated with diabetes, we reduced the expression of the deacetylase Sirt1 specifically in the fat body of Drosophila melanogaster." (PMID 35435227, 2022). "The study elucidates the SIRT1‐mediated molecular mechanisms underlying the close relationship between diabetes and Alzheimer's disease." (PMID 36073820, 2022). "In this study, we identified and analyzed a number of candidate modifiers of hyperglycemia in a previously characterized model of diabetes, Sirt1 loss of function." (PMID 35435227, 2022). "Related studies have shown that oxidative stress and PGC1α-mediated mitochondrial dysfunction are involved in the pathological changes of NAFLD lipid metabolism caused by SIRT1 silencing in type 2 diabetes mellitus." (PMID 36008973, 2022). "The aim of the study was to investigate the relationship between SIRT1 rs7069102 polymorphism and diabetic nephropathy (DN) in patients with type 2 diabetes mellitus (T2DM)." (PMID 33577446, 2021). "By stimulating the Akt/eNOS/NO and SIRT1/ER pathways, resveratrol was protected from diabetes-caused vascular disorders in C57BL/6 male mice fed with a 17-week high-fat diet." (PMID 33809718, 2021). "Down-regulation of SIRT1 caused by diabetes leads to the activation of NF-κB signaling, thereby promoting the activation of downstream inflammatory factors." (PMID 33995069, 2021). "SIRT1 has been linked with insulin sensitivity and glucose homeostasis and studies have shown that patients with diabetes had an 80% reduction in SIRT1 levels." (PMID 34639171, 2021). "It would be inferred that LBE supplementation has protective effects on hyperglycemia-induced renal damage by activation of AMPK/SIRT1 along with reduced NLRP3 inflammasome-associated hyper-inflammation in diabetes." (PMID 32050658, 2020). "In particular, hyperglycemia and diabetes cause the downregulation of SIRT1, thus resulting in inflammation, angiogenesis, an increase in oxidative stress, and vascular permeability, all of which are hallmarks of diabetic damage." (PMID 32722545, 2020). "The Nrf2/ARE pathway is a critical cellular anti-oxidant mechanism that is inactivated during chronic OS, including that associated with diabetes, and sirtuin-1 has a significant anti-oxidant effect because it activates the Nrf2/ARE pathway." (PMID 30707256, 2019).
diabetes (continued). "Metabolism of glucose and fatty acids produces NADH, which results in a reduction in the NAD+/NADH ratio under conditions of nutrient excess, such as diabetes, and is also associated with a reduction in the expression of sirtuin-1." (PMID 30707256, 2019). "The tocotrienol-rich fraction (TRF) also prevented muscle atrophy associated with diabetes by regulating insulin signaling via the AMPK/SIRT1/PGC-1α pathways in type 2 diabetic mice." (PMID 30275871, 2018). "We demonstrated that moderate exercise training successfully inhibited muscle atrophy-related ubiquitin ligase, MuRF-1, in association with suppression of NF-κB and activation of SIRT1, thereby attenuating protein degradation in diabetes." (PMID 29896118, 2018). "Sirt1 deletion caused renal injury in diabetes through increasing the expressions of endothelin-1 and TGF-β131." (PMID 29700282, 2018). "A close connection between SIRT-1 and p53ac has been reported, primarily in diabetes-associated vascular dysfunction/inflammation." (PMID 29330620, 2018). "This study was aimed at identifying diabetes-related genes and cellular pathways linked to changes of leukocyte SIRT1 expression at the time of GDM diagnosis." (PMID 30513672, 2018). "Sirtuin-1 (SIRT-1) down-regulation in type 2 diabetes mellitus (T2DM) has been associated with epigenetic markers of oxidative stress." (PMID 29330620, 2018). "As a matter of fact, SIRT1 also controls mitochondrial function and biogenesis, and free radical formation, key cues associated with epigenome reprogramming in diabetes." (PMID 29330620, 2018). "Our previous study showed that interaction between AMPK and sensor class III histone deacetylase sirtuin 1 (Sirt1), (interact to cause) caused endothelial damage and induced apoptosis in experimental diabetes." (PMID 29213353, 2017). "A genome-wide association study performed on Scandinavian subjects with diabetes showed a strong association between body weight and a marker in the SIRT1 locus." (PMID 27104517, 2016). "Previous studies have shown that some SIRT1 single-nucleotide polymorphisms (SNPs) are associated with body mass index, diabetes, blood pressure, cholesterol metabolism and coronary artery calcification." (PMID 27841908, 2016). "Insights into the regulation of SIRT1 has strong medical relevance because disruption of SIRT1 can cause cancer, diabetes and neurodegenerative diseases such as Alzheimer's, Parkinson’s, and Huntington’s diseases." (PMID 26468954, 2015). "Sirt1 is also believed to be a potent protector from ageing-associated pathologies, such as diabetes and cardiovascular disease." (PMID 26046931, 2015). "Our study identifies a potential route for therapeutic modulation of SIRT1 protein levels in SIRT1-linked diseases including cancer, neurodegeneration, and diabetes." (PMID 25541949, 2014). "This was exemplified by a case study of the involvement of miR-181 and diabetes mellitus, which revealed glutamate decarboxylase 2 and sirtuin-1 as likely causal molecular links between the miRNA and the disease." (PMID 24273243, 2014). "Misregulation of SIRT1 is implicated biochemically and genetically in diabetes and has been proposed as a therapeutic target in neurodegeneration, osteoarthritis and cardiovascular disease." (PMID 24258275, 2013). "We demonstrated in this study that alteration in the acetylation status of a transcription factor, Foxo4, is linked to a reduction in the expression of Sirt1 and contributes to the development of podocyte loss in diabetes." (PMID 21858169, 2011). "The potent beneficial effects of Sirt1 in protecting frommetabolic syndrome and its associated pathologies, such as diabetes and fattyliver, have consistently emerged in a variety of mouse models as one of themain physiological activities of Sirt1." (PMID 20562473, 2010).
diabetes (continued). "We, therefore, conducted the present study to investigate SIRT1 variants in the context of a controlled lifestyle intervention in prediabetic individuals at high risk for later onset of diabetes." (PMID 19014491, 2008). "This is the first study to have analysed the impact of SIRT1 genetic variants on the outcome of a lifestyle intervention in a diabetes risk population." (PMID 19014491, 2008). "The only genetic study that assessed SIRT1 genetic variants in the context of metabolism and diabetes reports an association of SIRT1 genetics with basal energy expenditure in Finnish type 2 diabetic patients." (PMID 19014491, 2008). "In addition to histones, mammalian SIRT1 targets numerous other proteins, including a large array of transcription factors, and thus has been implicated in multiple diseases, including diabetes." (PMID 39861104, 2025). "Moreover, empagliflozin showed significant effects on microvascular complications associated with diabetes mellitus by modulating the SIRT1/AMPK pathway within mitochondrial networks." (PMID 40076724, 2025). "So, future work can be focused on studying SIRT1 expression in relation to SIRT1 variants and also investigation the methylation status of SIRT1 in relation to lifestyle in healthy individuals and in patients with chronic diseases such as diabetes." (PMID 39474345, 2024). "SIRT1 regulates various cellular functions and is considered as a potential target for aging-associated disorders like Alzheimer ́s disease, Parkinson ́s disease, cardiovascular disease, osteoporosis, and diabetes." (PMID 38474862, 2024). "However, only resveratrol, a natural SIRT1 activator and few synthetic SIRT1 activators have been utilized clinically to lower the risk in patients with cardiovascular diseases, diabetes, cancer, sleep disorders, ulcerative colitis, atherosclerosis, and AD." (PMID 38416341, 2024). "In addition, exercise also alleviates the progression of many diseases by upregulating Sirt1, such as inflammation and metabolic dysfunction of the liver and kidney caused by diabetes, myocardial ischemia/reperfusion injury and hypothalamic inflammation." (PMID 36882837, 2023). "Additionally, it has been found that diminished SIRT1 activity causes diabetes and metabolic syndrome (Chalkiadaki and Guarente, 2012)." (PMID 37534224, 2023). "Decreased levels of Sirtuin 1 have been shown to be associated with the diagnosis of diabetes mellitus, nonalcoholic fatty liver disease, and the metabolic syndrome, in which epigenetic modifications may play an important role." (PMID 37854188, 2023). "However, the mechanisms underlying the changes in the SIRT1–eNOS axis mediated by aging and diabetes in endothelial cells (ECs) remain obscure." (PMID 36789048, 2023). "Additionally, it has been reported that a decrease in Sirt1 and Sirt3 levels in diabetes can cause cardiac complications by acting on mitochondrial proteins." (PMID 38134189, 2023). "Considering that the upregulation of SIRT1 inhibits the ER stress pathway, it is possible that H2S could improve diabetes-associated cognitive deficits by inhibiting hippocampal ER stress through upregulating SIRT1." (PMID 36978900, 2023). "Indeed, the role of Sirtuin 1 is critical to glucose tolerance and the metabolic syndrome in children and Sirtuin 1 dysregulation is linked to diabetes and various chronic diseases." (PMID 38107514, 2023). "Given its relevance to reproductive health, perturbation in Sirt1 activity might underlie the molecular bases for fertility impairments, which is evident by miR-34a in diabetes mellitus (DM) induced testicular apoptotic cell death (TACD)." (PMID 35067179, 2022). "Few studies have reported the genetic variants in the Sirt1 and Nrf2 genes (Sirt1 rs7895833 A > G, Sirt1 rs2273773 C > T and Nrf2 rs6721961 C > A) that increase the risk of type 2 diabetes mellitus and are correlated with some glycemic and metabolic traits in the Chinese Han population." (PMID 35365152, 2022).
diabetes (continued). "In addition, a study has confirmed that diabetes-induced downregulation of Sirt1 leads to reduced autophagy and accelerated risk of DN." (PMID 35614465, 2022). "Hence, we present evidence that LYPLAL1-DT effectively protects against vascular endothelial injury in diabetes associated complications via the LYPLAL1-DT -miR-204-5p/SIRT1 pathway." (PMID 35508613, 2022). "Some of these observations could be a consequence of reduced SIRT1 expression in the hearts from offspring of STZ-induced diabetes dams that is associated with hypermethylation of the Sirt1 gene." (PMID 35457285, 2022). "SIRT1 is a nicotinamide adenosine dinucleotide (NAD)-dependent multifunctional deacetylase that removes acetyl groups from many proteins that can be implicated in diabetes." (PMID 35346383, 2022). "SIRT1 deficits are associated with diabetes mellitus and kidney diseases." (PMID 35655597, 2022). "For instance, AMPK activation induced by metformin treatment or by endurance exerise alleviates ER stress and oxidative stress in ECs to combat diabetes-associated vascular dysfunction; and resveratrol-induced SIRT1 activation also improves vascular function in diabetes." (PMID 35883777, 2022). "SIRT1 plays a major role in the regulation of metabolic homeostasis, and as a result, any changes causing downregulation can stimulate pathways leading to chronic complications of diabetes mellitus and its comorbidities." (PMID 36225477, 2022). "We hypothesize that modulation of Sirt1 and Sirt3 protein activity independently or in a combination may improve mitochondrial function as well as diabetes-associated cardiac complications." (PMID 33668369, 2021). "Taken together our results conclude that activation of Sirt1 alone could be a potential therapeutic target for diabetes-associated cardiovascular complications." (PMID 33668369, 2021). "In diabetes, SIRT-1 is downregulated, which is often associated with endothelial dysfunction." (PMID 34149611, 2021). "SIRT1 is as key epigenetic regulator of p66Shc expression, a mitochondrial adaptor implicated in ROS accumulation, derangement of mitochondrial function, insulin resistance and diabetes." (PMID 34698884, 2021). "Diabetes-induced disruption of the SIRT1-LXR axis and reduced oxysterol production due to loss of cytochromes P450, 27A1, and 46A1 in the retina result in diminished cholesterol removal leading to inadequate vascular repair, macrophage/microglia activation, and widespread retinal pathology." (PMID 33581416, 2021). "It has been shown that overexpression of SIRT1 reduces insulin resistance and its gene mutation may induce type 1 diabetes mellitus." (PMID 34656137, 2021). "Interestingly, the depletion of nicotinamide adenine dinucleotide (NAD+) in diabetes not only causes upregulation of xanthine oxidase but also downregulation of SIRT1." (PMID 32404204, 2020). "Berberine attenuated oxidative stress in mice with diabetes partly by miR-106b/SIRT1 pathway and the islets activity that can be effective to reduce the cardiovascular risk factors and encephalopathy improvement via the SIRT1/ER stress pathway in diabetes." (PMID 33235706, 2020). "Thus, activation of NRF2/SIRT1 pathway is an effective therapeutic strategy and will open new directions for diabetes and associated complications." (PMID 33096729, 2020). "We speculate that decreased AMPK and Sirt1 activity is involved in the development of diabetes-associated cognitive dysfunction and decline in synaptic plasticity-associated proteins." (PMID 30911292, 2019). "In addition, diabetes, HG, and palmitate stimulate p66Shc, which activates a redox mechanism that upregulates miR-34a expression, targeting sirtuin-1 for degradation, and causing endothelial dysfunction." (PMID 30707256, 2019).
diabetes (continued). "Naturally-occurring products have yielded many valuable drugs, such as resveratrol, curcumin, EGCG, small-molecule SIRT1 activators, and many other compounds currently used to treat age-associated diseases including cancer, diabetes, cardiovascular disease, and neurodegenerative diseases." (PMID 31920540, 2019). "Finally, retinal inflammation was induced with downregulation of the adenosine monophosphate (AMP) activated protein kinase (AMPK) pathway and NF-κB activation associated with SIRT1 deactivation in diabetes." (PMID 31287252, 2019). "In the present study, we hypothesized that melatonin attenuates renal I/R injury in diabetes by activating silent information regulator 2 associated protein 1 (SIRT1) expression and Nrf2/HO-1 signaling." (PMID 30578379, 2019). "The underlying mechanisms by which HG conditions regulate SIRT1 expression in PTs in diabetes remain unclear." (PMID 29717156, 2018). "Thus, AMPK/Sirt1 pathway plays an important role in microvascular damage associated with diabetes, including DR." (PMID 29213353, 2017). "Thus, evidence has shown that activating AMPK and SIRT1 induces the concurrent deacetylation and phosphorylation of their target molecules and decreases susceptibility to diabetes-associated disorders." (PMID 29238727, 2017). "In three independent Japanese populations with T2DM (1502 cases and 1740 controls), the SIRT1 rs2236319 (A/G), rs10823108 (A/G), rs3818292 (A/G) and rs4746720 (C/T) variants were associated with a risk of diabetes, while selected SNPs in SIRT2, SIRT3, SIRT4, SIRT5 and SIRT6 were not." (PMID 27104517, 2016). "SIRT1 mediated suppression of NF-κB dependent pro-inflammatory transcription, via lysine deacetylation of p65, is considered a central mechanism underlying its protective roles in a range of human diseases including atherosclerosis, stroke, and diabetes." (PMID 27285989, 2016). "Similarly, activation of SIRT1 mitigates syndromes such as diabetes, neurodegenerative diseases, liver steatosis, bone loss, and inflammation." (PMID 25541949, 2014). "With SIRT1 implicated in diseases such as cancer, diabetes and neurodegeneration, greater understanding of its endogenous regulation could also lead to opportunities for therapeutic intervention." (PMID 24258275, 2013). "Interestingly, new studies have linked mTOR signaling to the cell longevity pathways of SIRT1 that can also provide robust cardiovascular protection against models of experimental diabetes." (PMID 22545721, 2012). "Strategies to preserve Sirt1 expression or reduce Foxo4 acetylation could be used to prevent podocyte loss in diabetes." (PMID 21858169, 2011). "Although the cross-sectional study let rather doubt that SIRT1 does represent a classical diabetes risk gene, SIRT1 genetic variants may determine the individual response to a lifestyle intervention." (PMID 19014491, 2008). "Consequently, SIRT1 dysregulation has been implicated in diabetes and thereby, it may be considered as a therapeutic target for some debilitating diseases, for example, neurodegeneration, osteoarthritis, cardiovascular disease, and diabetic complications." (PMID 39980831, 2025). "Moreover, SIRT1 has been proven to be beneficial in diabetes, metabolic disorders, and many age-associated pathophysiological changes, as it is engaged in regulating fat and glucose metabolism, inflammatory response, cell survival, oxidative stress, and adipogenesis." (PMID 41301404, 2025). "SIRT1 deficiency has been associated with diabetes, and a variant of the SIRT1 gene has been found to be involved in human autoimmune diabetes; however, it is unclear whether this genetic variation exists in Han Chinese with type 1 diabetes (T1D) and whether it contributes to development of T1D." (PMID 37695462, 2024).